PTH (parathyroid hormone)
Diseases named in the same sentence as PTH in open-access papers (continued):
Sharing a sentence is not in itself a finding about the gene and the disease.
multiple myeloma (continued). "Because DKK1 is expressed by Hg myeloma cells and PTH treatment resulted in reduced growth of these cells in myelomatous bones, DKK1 downregulation could be a result of direct effects of PTH on osteoblasts, it could be an epiphenomenon of reduced tumor burden, or it could be a combination of both." (PMID 21188144, 2010). "Beta-2 microglobulin, parathyroid hormone (PTH), angiotensin-converting enzyme (ACE), and myeloma screen were negative." (PMID 40951148, 2025). "After 4 weeks of PTH treatment (before injection of myeloma cells), BMD of the implanted nonmyelomatous rabbit bones was 60±16% higher than levels before PTH treatment (p<0.0001)." (PMID 21188144, 2010).
Stroke (22 papers, 2013 to 2025). Sudden impairment of blood flow to a part of the brain due to occlusion or rupture of an artery to the brain. "Since elevated parathyroid hormone levels have been found in stroke patients, an association between parathyroid hormone (PTH) levels and cerebrovascular diseases is presumable." (PMID 36678205, 2023). "Parathyroid hormone (PTH) and 25-dihydroxyvitamin D levels together can make important contributions to determination of stroke risk." (PMID 36569944, 2022). "In peritoneal dialysis patients, lower serum PTH levels were significantly associated with an increased risk of stroke." (PMID 36569944, 2022). "We seek to investigate the incidence of stroke and the role of parathyroid hormone and vitamin D supplementation in stroke risk among CAPD patients." (PMID 32423377, 2020). "The third result of our study was that PTH, 25(OH)D, and HT were the most powerful markers for the prediction of stroke risk, even when all other cardiovascular risk factors were included in the analysis." (PMID 28115793, 2017). "25(OH)D was the most powerful marker for the predicting the stroke risk, followed by HT and PTH, in descending order." (PMID 28115793, 2017). "PTH and 25(OH)D levels together can make important contributions to determination of stroke risk, and further investigations are needed to understand this relationship more fully." (PMID 28115793, 2017). "Different prediction models were used to examine the association between stroke and PTH, 25(0H)D levels." (PMID 28115793, 2017). "In contrast, the number of studies examining the association between increased PTH levels and cardiovascular diseases, mortality, and particularly, stroke is quite limited." (PMID 28115793, 2017). "This demonstrated that PTH is an important marker for defining stroke risk, but its predictive power is enhanced when used in conjunction with 25(OH)D." (PMID 28115793, 2017). "In an age- and sex-adjusted model, serum PTH levels were significantly associated with history of stroke (OR = 1.058, 95%CI 1.00–1.11, P = 0.025) indicating that risk for poststroke HF relative to 1 pmol/L increase in PTH increases by 5.8%." (PMID 24187647, 2013). "History of stroke was associated with higher levels of serum PTH (Pearson correlation coefficient r = 0.155, P = 0.010), vitamin B12 (r = 0.139, P = 0.027), urinary bone resorption marker DPD/Cr (r = 0.183, P = 0.004), and lower BSI (r = −0.170, P = 0.009)." (PMID 24187647, 2013). "Circulating 25(OH)D, PTH, phosphate, and vitamin B12 levels are linked to both stroke and HF, further accentuating their important underlying role in vascular and bone biology." (PMID 24187647, 2013). "First, it was determined whether PTH and 25(OH)D could be used as markers for predicting stroke risk." (PMID 28115793, 2017). "Both PTH and vitamin D appear to be separate risk factors for stroke." (PMID 28115793, 2017). "Additional studies are needed to investigate the effect of PTH on stroke risk, the interaction of both predictors, and possible conditions that may develop as a result of dysregulated vitamin D and PTH synthesis." (PMID 28115793, 2017). "In addition to 25(OH)D, PTH serum levels should be considered, and both predictors should be assessed in conjunction for more accurate determination of stroke risk." (PMID 28115793, 2017). "The second finding of our study was that both PTH and 25(OH)D levels were two important markers that could be used to predict the future risk of stroke." (PMID 28115793, 2017). "Bone marrow-derived endothelial progenitor cells and endothelial stem cells increased in the peripheral blood of stroke mice after PTH treatment." (PMID 36569944, 2022). "The effects of parathyroid hormone and vitamin D supplementation on stroke in CAPD patients was evaluated." (PMID 32423377, 2020).
Stroke (continued). "Our study investigated the prevalence of stroke among patients with CAPD and the role of serum PTH levels and vitamin D supplementation in stroke risk via a retrospective study with a long-term, single-center follow-up." (PMID 32423377, 2020). "In conclusion, PTH levels were increased, while 25(OH)D levels were decreased in patients with stroke." (PMID 28115793, 2017). "When the PTH level was used as the prediction marker, the accurate prediction rate was 35.6% for stroke patients, 81.8% for the controls, and 61.8% as an overall accurate prediction rate (wald = 8.129, p = 0.004)." (PMID 28115793, 2017). "In conclusion, a combined review of all analyses revealed that 25(OH)D was the most important factor for stroke prediction, followed by HT and PTH, in descending order." (PMID 28115793, 2017). "Different estimation models were designed in order to examine the relationship between PTH and 25(OH)D levels with stroke." (PMID 28115793, 2017). "Elevated PTH level predicts a greater likelihood of prevalent and incident CV events, including myocardial infarction (MI), stroke, and CV death." (PMID 27284924, 2016). "As this is the first report on this PTH therapy for ischemic stroke for the demonstration of the efficacy and feasibility, PTH treatment was initiated at 1 hr after stroke followed by repeated administrations for 6 days." (PMID 24503654, 2014). "Compared with stroke-vehicle control mice, the levels of pro-angiogenic factors VEGF, EPOR, Tie-1 and the neurotrophin BDNF significantly increased in PTH treated mice (n = 3 in stroke and stroke plus PTH groups, respectively; P<0.05)." (PMID 24503654, 2014). "The scanning imaging showed that stroke mice that received PTH had significantly greater recovery of local blood flow compared with the stroke-saline group (n = 8 in stroke and the stroke plus PTH group; P<0.05)." (PMID 24503654, 2014). "Using flow cytometry and double labeling with CD34 and Flk-1, we confirmed a mobilized release of bone marrow ESCs/EPCs into the peripheral blood after 6-day PTH treatment in stroke mice." (PMID 24503654, 2014). "In stroke mice that received PTH, there was a much greater number of NeuN+/BrdU+ cells compared with the stroke controls (n = 6 in stroke and stroke plus PTH group, respectively; P<0.05)." (PMID 24503654, 2014). "In PTH-treated mice, the time-to-detect and the time to remove were both significantly improved compared to stroke-saline controls (n = 11–20 in stroke and stroke plus PTH groups at different time points; P<0.05)." (PMID 24503654, 2014). "There was, however, a significant increase in the expression of migration chemoattractant SDF-1 in the PTH treatment group compared with the stroke control group." (PMID 24503654, 2014). "While this possibility exists, since the animal model of barrel cortex stroke in our investigation is a “mini-stroke” model that only affects a small restricted part of the cortex, the leakage of PTH in this model should be minimum." (PMID 24503654, 2014). "Stroke mice that received PTH treatment showed a marked increase, i.e. more than double the amount in controls, of CD34+/Flk1+ cells in peripheral blood (P<0.05)." (PMID 24503654, 2014). "In summary, PTH treatment after stroke can mobilize ESCs/EPCs from the bone marrow into peripheral blood circulation." (PMID 24503654, 2014). "PTH treatment increased the Glut-1+ vessel staining 14 days after stroke (n = 6 in stroke and the stroke plus PTH group, respectively; P<0.05)." (PMID 24503654, 2014). "We expect that even more delayed treatment of PTH, e.g. several hrs after stroke, can be beneficial in promoting chronic angiogenesis and other tissue repair process." (PMID 24503654, 2014). "The number of DCX+/BrdU+ cells was significantly greater in stroke mice that received PTH treatment (n = 7) than in stroke-saline mice (n = 6)." (PMID 24503654, 2014).
Stroke (continued). "Six days after stroke and PTH or saline treatment, expression of regenerative factors VEGF, EPO receptor (EPOR), Ang-1, Tie-1, Flk-1, BDNF and SDF-1 in the ischemic peri-infarct region were analyzed using Western blotting." (PMID 24503654, 2014). "Compared with the stroke-saline group, the mice receiving PTH treatment showed significantly more Glut-1+/BrdU+ microvessels, suggesting increased formation of new vessels or angiogenesis in the post-stroke brain." (PMID 24503654, 2014). "PTH-treated mice showed significantly better sensorimotor functional recovery compared to stroke controls." (PMID 24503654, 2014). "The increased local cerebral blood flow 14 days after stroke and PTH treatment was mostly likely due to increased regeneration such as angiogenesis during the chronic phase after stroke." (PMID 24503654, 2014). "A univariate analysis including age, stroke comorbidity, APACHE II, septic shock, total calcium, albumin, 25(OH)D, 1,25(OH)2D, and PTH was performed for their clinical or statistical association with 30-day mortality." (PMID 23741318, 2013). "Higher PTH levels have been previously observed in stroke patients." (PMID 31830923, 2019). "Since all these data suggest that increased PTH levels may increase risk for cerebrovascular disease, the aim of this study was to investigate the correlation between PTH levels and stroke and to study 25(OH)D because of its close correlation with PTH." (PMID 28115793, 2017). "Those hemodialysis patients with DM were older, shorter dialysis vintage, with more cigarette smoking, higher prevalence of co-morbidity of CAD, PAOD, stroke, and lower serum level of creatinine, intact parathyroid hormone (i-PTH), Kt/V and urea reduction rate (URR)." (PMID 25051062, 2014). "Thus, the hypercalcemic effect or other side effects of the PTH therapy demonstrated in stroke animals is likely to be mild and transient." (PMID 24503654, 2014). "Many of these factors are up-regulated in the stroke mice that received PTH." (PMID 24503654, 2014). "In multiple regression analyses adjusted for age, sex, HF type, 25(OH)D, PTH, eGFR, calcium, phosphate, and magnesium, history of stroke was an independent determinant of both higher DPD/Cr levels (β = 3.87, 95%CI 1.11–6.64, P = 0.006) and lower BSI (β = −4.17, 95%CI −7.29–1.06, P = 0.027)." (PMID 24187647, 2013). "In addition, potential confounding factors, including serum PTH and calcium might influence the relationship between 25(OH) D and stroke outcomes." (PMID 29437901, 2018). "Vitamin D and PTH might influence stroke outcomes through divergent pathway." (PMID 29437901, 2018). "However, studies have predominantly reported that increased PTH caused vascular abnormalities rather than stroke and mentioned it as a risk factor for cardiovascular disorders." (PMID 28115793, 2017). "To demonstrate that the PTH-promoted angiogenesis could result in functional vasculatures, we measured the local cerebral blood flow using a Laser Doppler Scanner at 14 days after stroke." (PMID 24503654, 2014). "For the mediator models based on the categorical weight change variable, we identified age, smoking, alcohol use, walking, COPD, stroke, estrogen use, IGF-1, 25(OH)D, albumin, height, ln-SHBG, and ln-PTH as confounders." (PMID 34272641, 2022). "As for Ca, which was proven to prevent stroke and extend lifespan in SHRSP, low Ca intake decreases plasmatic Ca concentration, which stimulates parathyroid hormone (PTH) and renin, angiotensin, and aldosterone secretion to raise BP." (PMID 36428542, 2022). "We analyzed the relationship between stroke and several laboratory parameters such as CRP, intact parathyroid hormone (PTH), Kt/V, and URR as a measure of low molecular toxins removal by the HD." (PMID 34068165, 2021). "Few studies have focused on the relationship between stroke and CAPD, especially the role of PTH and vitamin D supplementation for stroke in patients with CAPD." (PMID 32423377, 2020).
Stroke (continued). "Moreover, in the PTH-treated ischemic brain, the neuroblast migration distance from SVZ was also significantly longer compared with that in stroke-saline group." (PMID 24503654, 2014).
Graves disease (20 papers, 2014 to 2026). Graves' disease is an autoimmune disorder that leads to overactivity of the thyroid gland (hyperthyroidism).It is caused by an abnormal immune system response that causes the thyroid gland to produce too much thyroid hormones. "Most surgical indications for our patients with tumors were peritracheal or lateral neck malignancies requiring lymph node dissection, which tend to have decreased postoperative PTH levels compared with Graves’ disease." (PMID 38803480, 2024). "PTH on POD1 emerged as a significant predictor for early recovery (OR 1.13 (95% CI 1.06–1.2) p < 0.001) when controlled for Graves’ disease and visualization of all PGs." (PMID 35683589, 2022). "Process measures included serum calcium measurement 6−12 hours postoperatively; parathyroid hormone measurement 6 hours postoperatively; preoperative iodine for Graves disease, and postoperative prophylactic calcium carbonate administration." (PMID 35720874, 2022). "A 22-year-old female was diagnosed as Graves’ disease with obviously elevated serum calcium and reduced parathyroid hormone levels." (PMID 32605565, 2020). "A 58-year-old female patient was found to have Graves’ disease, a marked elevated serum calcium level (adjusted serum calcium: 3.74 mmol/L), and reduced parathyroid hormone level." (PMID 28121960, 2017). "While PTH on POD 1 evolved as a predictor of early recovery of PH, later recovery was associated with visualization of all PTGs during surgery when controlled for Graves’ disease and female gender." (PMID 35683589, 2022). "The patient also had Graves’ disease and elevated PTH levels." (PMID 34022862, 2021). "Clinicians should maintain a high index of suspicion for parathyroid malignancy in patients with Graves' disease who present with a neck mass, even if calcium and PTH levels do not reach the extreme thresholds typically associated with carcinoma." (PMID 42152350, 2026).
hyperplasia (20 papers, 2006 to 2025). An abnormal increase in the number of cells in an organ or a tissue with consequent enlargement. "A recent study revealed that dialysis duration, parathyroid gland volume, and serum PTH were risk factors for nodular hyperplasia of parathyroid glands in SHPT." (PMID 32816132, 2021). "PTH decline >60 % diagnosed hyperplasia with specificity of 100 %." (PMID 26542689, 2015).
osteoarthritis (20 papers, 2013 to 2026). A noninflammatory degenerative joint disease occurring chiefly in older persons, characterized by degeneration of the articular cartilage, hypertrophy of bone at the margins and changes in the synovial membrane. "For instance, elevated levels of parathyroid hormone have been shown to be causally linked to a decreased risk of osteoarthritis." (PMID 39172202, 2024). "On the other hand, six markers were genetically predictive of causality and linked to a reduced risk of osteoarthritis, such as X-11,423-O-sulfo-L-tyrosine, ADpSGEGDFXAEGGGVR, parathyroid hormone, and retinol." (PMID 39172202, 2024). "The results suggest that PTH is able to correct the errors in bone remodeling caused by osteoarthritis, and that this drug could potentially alleviate patients’ chronic pain." (PMID 33646122, 2021). "PTH also slowed down the progression of osteoarthritis, by preventing the cartilage on the subchondral layer from deteriorating as quickly." (PMID 33646122, 2021). "We found that subchondral sensory innervation for osteoarthritis pain was significantly decreased in PTH-treated DMM mice compared with vehicle-treated DMM mice." (PMID 33646122, 2021). "To validate the role of PTH-induced remodeling of subchondral bone in the attenuation of osteoarthritis pain and osteoarthritis progression, we induced conditional knockout of PTHIR in Nestin+ MSCs of DMM mice." (PMID 33646122, 2021). "OARSI score increased progressively in DMM mice over 8 weeks, but this progression was reduced and slower in PTH mice, indicating that early initiation of iPTH in osteoarthritis slowed the progression of articular cartilage degeneration." (PMID 33646122, 2021). "The newly formed osteoid islets in the subchondral bone marrow were almost diminished in osteoarthritis mice with daily PTH injection." (PMID 33646122, 2021). "In general, PTH attenuate osteoarthritis by maintaining microarchitecture of the subchondral bone and protection of articular cartilage." (PMID 33646122, 2021). "Collectively, these results indicate that aberrant subchondral bone formation due to elevated TGF-β1 signaling in osteoarthritis was attenuated in the setting of PTH-induced endocytosis of TβRII." (PMID 33646122, 2021). "Here, we show that intermittent parathyroid hormone (iPTH) attenuates osteoarthritis pain by inhibiting subchondral sensory innervation, subchondral bone deterioration, and articular cartilage degeneration in a destabilized medial meniscus (DMM) mouse model." (PMID 33646122, 2021). "PTH-induced osteoarthritis pain relief is inhibited by PTH type one receptor knockout on Nestin+ MSCs." (PMID 33646122, 2021). "Previous studies have demonstrated an inverse association between parathyroid hormone (PTH) and the risk of osteoarthritis (OA)." (PMID 34381493, 2021). "More importantly, the beneficial effect of PTH on subchondral bone deterioration and pain relief was diminished in the osteoarthritis Pth1r−/− mice." (PMID 33646122, 2021). "An effect on induction of chondrogenesis with increased collagen type II was previously confirmed using a single concentration of PTH in growth plate chondrocytes and MSCs from osteoarthritis patients." (PMID 25079095, 2014). "Several animal studies have shown that PTH has therapeutic potential for cartilage regeneration and protection as well as inhibition of progression of osteoarthritis." (PMID 25079095, 2014). "This further supports the systemic intermittent PTH administration for the treatment of cartilage defects and osteoarthritis." (PMID 24058535, 2013). "Importantly, PTH also attenuated osteoarthritis progression by inhibiting deterioration of subchondral bone microarchitecture and cartilage degeneration." (PMID 33646122, 2021). "The studies on PTH effect on osteoarthritic subchondral bone showed iPTH administration resulted in improvement of subchondral bone structure or contradict result of induction of osteoarthritis." (PMID 33646122, 2021).